USP10 (ubiquitin specific peptidase 10)
Diseases named in the same sentence as USP10 in open-access papers (continued):
Sharing a sentence is not in itself a finding about the gene and the disease.
bone marrow failure (2 papers, 2016 to 2018). "In this article, Fujii, Higuchi, and colleagues show that systemic USP10-knockout (USP10-KO) mice develop bone marrow failure associated with marked reductions in long-term hematopoietic stem cells (LT-HSCs)." (PMID 27974222, 2016). "Ubiquitin-specific protease 10 (USP10) is a deubiquitinase that is ubiquitously expressed in many cell types, and a genetic knockout of Usp10 in mice leads to bone marrow failure and death at an early age." (PMID 30469013, 2018).
Cerebral ischemia (2 papers, 2021 to 2023). Restriction of arterial blood supply to the brain associated with insufficient oxygenation to support the metabolic requirements of the tissue. "Low expression of USP10 induced by cerebral ischemia/reperfusion is associated with brain injury, and increased USP10 expression has a protective effect against cerebral ischemia injury by inhibiting inflammation and apoptosis through blocking TAK1 signal transduction." (PMID 34412625, 2021).
chronic obstructive pulmonary disease (2 papers, 2020). A chronic and progressive lung disorder characterized by the loss of elasticity of the bronchial tree and the air sacs, destruction of the air sacs wall, thickening of the bronchial wall, and mucous accumulation in the bronchial tree. "Pseudomonas aeruginosa virulence factor Cif, found in patients with CF and chronic obstructive pulmonary disease (COPD), suppresses USP10 activity and promotes CFTR ubiquitylation and lysosomal degradation." (PMID 32331485, 2020).
esophageal cancer (2 papers, 2022). A primary or metastatic malignant neoplasm involving the esophagus. "In esophageal cancer and human neuroblastoma, USP10 affects cancer cell proliferation by stabilizing PCNA and NRF-1, respectively." (PMID 35627217, 2022).
keloid (2 papers, 2021 to 2022). An irregularly shaped, elevated mark on the skin caused by deposits of excessive amounts of collagen during wound healing.
multiple myeloma (2 papers, 2022 to 2026). "Moreover, Pseudokinase TRIB3 promotes multiple myeloma progression by stabilizing SSRP1 through USP10-mediated deubiquitination, thereby enhancing oncogenic signaling and tumor growth." (PMID 41522354, 2026).
non-alcoholic fatty liver disease (2 papers, 2020 to 2023). "Among them, miR-34a-5p acted as a negative regulator of nonalcoholic fatty liver disease by targeting USP10." (PMID 37915040, 2023).
Obesity (2 papers, 2024 to 2025). Accumulation of substantial excess body fat. "Mining public datasets revealed that USP10 expression is substantially increased in the adipose tissue (AT) from individuals with obesity." (PMID 41417444, 2025). "This study provides compelling evidence that spautin-1 exerts anti-obesity effects in part by inhibiting USP10 and destabilizing C/EBPβ in adipose tissue." (PMID 41417444, 2025). "Consistently, in mouse adipose tissue, the mRNA and protein levels of USP10 were increased in obesity, whereas USP13 revealed a high Ct by RT-qPCR and was undetectable by immunoblot, which aligns with FANTOM5 (FF:10010-101C1)." (PMID 41417444, 2025). "Together, these results demonstrate that USP10 is a key DUB associated with adipogenesis and obesity, which serves as the functional target of spautin-1 in adipose tissue." (PMID 41417444, 2025). "Several USPs, including USP2, USP10, USP14, USP15, USP18, and USP22, have been associated with obesity and related metabolic disorders." (PMID 38322269, 2024). "To test this hypothesis, we integrated the mining of public adipose-tissue datasets with in vitro adipocyte differentiation assays, pharmacologic perturbation, and the genetic manipulation of USP10/USP13 and evaluated the anti-obesity efficacy in a high-fat diet mouse model." (PMID 41417444, 2025). "Importantly, the pharmacology of spautin-1 extends beyond USP10 inhibition, which might contribute to its anti-obesity efficacy and yield outcomes that do not fully mirror the tissue-selective USP10 suppression." (PMID 41417444, 2025). "Analysis of publicly available RNA-sequencing datasets (GSE213058 and GSE235696) revealed that USP10, but not USP13, was elevated in adipose tissue from adults with obesity compared with that of lean controls, with a bias toward VAT over SAT." (PMID 41417444, 2025).
osteoporosis (2 papers, 2023 to 2025). A condition of reduced bone mass, with decreased cortical thickness and a decrease in the number and size of the trabeculae of cancellous bone (but normal chemical composition), resulting in increased fracture incidence. "In this study, we aimed to explore the mechanisms involved in carbamazepine (CBZ) and microRNA (miR)-20a-5p/ubiquitin-specific peptidase 10 (USP10)/S-phase kinase-associated protein 2 (SKP2) axis in osteoporosis." (PMID 37915040, 2023). "In this study, we treated BMSCs with CBZ and constructed cell lines that interfered with or overexpressed miR-20a-5p, USP10 and SKP2 to explore the effects of CBZ by regulating miR-20a-5p/USP10/SKP2 axis on osteoporosis." (PMID 37915040, 2023). "Due to time and funding constraints, we only conducted in vitro studies on the mechanism of CBZ and miR-20a-5p/USP10/SKP2 axis in osteoporosis." (PMID 37915040, 2023). "In the future, we will further verify the mechanism of CBZ and miR-20a-5p/USP10/SKP2 axis in osteoporosis in animal models." (PMID 37915040, 2023). "In our study of osteoporosis, we found that miR-20a-5p could bond to USP10 and repress its expression." (PMID 37915040, 2023). "Additionally, gene therapy approaches targeting key regulatory enzymes like USP7 and USP10 could offer novel therapeutic strategies for osteoporosis." (PMID 40427572, 2025). "CBZ regulated USP10 through miR-20a-5p to affect the deubiquitination of SKP2 and inhibit osteogenic differentiation, which provided a new idea for osteoporosis treatment." (PMID 37915040, 2023). "Currently, there is no report on the mechanism of CBZ in osteoporosis through the miR-20a-5p/USP10/SKP2 axis, which is first reported in this study." (PMID 37915040, 2023).
prostate tumor (2 papers, 2016 to 2021). "We speculate that the discordant effects on AR-mediated transcription observed between the siRNA luciferase screen and reported AR coregulator functions of MDM2, RNF6, and USP10 in prostate tumor cells are due to differences in prostate tumor cell lines and reporter vectors." (PMID 27365400, 2016).
Sepsis (2 papers, 2021 to 2025). Sepsis is defined as life-threatening organ dysfunction caused by a dysregulated host response to infection. "However, it remains unknown whether DUB inhibitors that target USP10 could make the recipients of other clinical conditions more susceptible to sepsis and this warrants further investigation." (PMID 34412625, 2021). "USP10-mediated deubiquitination of FOXQ1 ameliorates kidney injury in sepsis mice induced by CLP and LPS by targeting the CREB5/NF-κB axis, thereby alleviating inflammation and apoptosis in HK-2 cells." (PMID 40989844, 2025). "In a mouse model of AKI, USP10 alleviates sepsis-induced oxidative stress in renal tissue by enhancing the stability of SIRT6 and activating the NRF2/ARE signaling pathway." (PMID 40989844, 2025). "Our study revealed that USP10 attenuated sepsis-induced oxidative stress in kidney tissues and activated the NRF2/ARE signaling pathway." (PMID 34412625, 2021). "In this study, we examined the expression of USP10 in kidney tissues of sepsis-induced AKI mouse models, and explored the function of USP10 in sepsis-induced renal dysfunction and renal tubular epithelial cells." (PMID 34412625, 2021). "In this study, the mechanism by which ubiquitin specific peptidase 10 (USP10) reduces sepsis-induced AKI was investigated." (PMID 34412625, 2021). "Our study reports for the first time that USP10 alleviates sepsis-induced renal dysfunction, and reduces renal tubular epithelial cell apoptosis and oxidative stress." (PMID 34412625, 2021). "USP10 alleviates sepsis-induced renal dysfunction and reduces renal tubular epithelial cell apoptosis and oxidative stress." (PMID 34412625, 2021). "In conclusion, our findings show that USP10 expression is decreased in kidney tissues of sepsis-induced AKI mouse models." (PMID 34412625, 2021). "USP10 overexpression alleviates sepsis-induced renal dysfunction and reduces damage in renal tubular epithelial cells." (PMID 34412625, 2021). "In the present study, we found that Sirt6-mediated Nrf2/ARE signaling alleviates sepsis-induced AKI via USP10." (PMID 34412625, 2021). "Altogether, these findings illustrate that USP10 alleviates sepsis-induced AKI by regulating Sirt6-mediated Nrf2/ARE signaling pathway, proposing a novel target for the clinical treatment of AKI." (PMID 34412625, 2021). "Moreover, USP10 attenuates sepsis-induced oxidative stress in renal tissues by increasing SIRT6 stability and activating the NRF2 /ARE signaling pathway." (PMID 34412625, 2021). "In addition, the role of USP10 in sepsis-induced oxidative stress in renal tissues via SIRT6-mediated NRF2 /ARE signaling pathway was investigated." (PMID 34412625, 2021). "However, the role of USP10 in sepsis-induced organ damage is unclear, AKI in particular, which requires further investigation." (PMID 34412625, 2021). "USP10 is expressed in both sepsis and acute respiratory syndrome patients." (PMID 34412625, 2021). "Thus, our findings suggest that USP10 may be a potential therapeutic target in sepsis-induced AKI." (PMID 34412625, 2021).
tauopathy (2 papers, 2022 to 2025). Neurodegenerative disorders involving deposition of abnormal tau protein isoforms (tau proteins) in neurons and glial cells in the brain. "As one of the important de-ubiquitinating enzymes, USP10 is reported to be involved in tauopathy but its role in AD is not well understood." (PMID 35987808, 2022). "Furthermore, interfering with USP10-Tau interaction reversed the tauopathy induced by USP10 overexpression and Aβ oligomers treatment." (PMID 35987808, 2022). "Inhibition of USP10-Tau interaction might be therapeutically useful in the management of AD and related tauopathies." (PMID 35987808, 2022). "Therefore, together, our results identify the role of the USP10-mediated amyloidogenic pathway in tauopathy." (PMID 35987808, 2022). "Therefore, we thought that the interfering peptides would be functionally beneficial in attenuating tauopathy induced by USP10 overexpression or triggered by Aβ in primary cells." (PMID 35987808, 2022). "Based on these observations, it is tempting to postulate that USP10 is involved in tauopathy, but how it promotes AD pathogenesis remains unclear." (PMID 35987808, 2022). "Targeting USP7 and USP10 may offer a novel therapeutic strategy for AD and related tauopathies." (PMID 41303552, 2025). "Therefore, we thought that the Tauopathy might likely be blocked or at least attenuated by interfering with the USP10-Tau interaction." (PMID 35987808, 2022). "The deubiquitinating enzymes Usp7 and Usp10 strongly influenced seeded TAU aggregation across various in vitro and ex vivo tauopathy models." (PMID 41303552, 2025). "We have also complemented the Aβ-mediated approach to Tau pathology involving USP10, and also opened new avenues for the development of small interfering peptides that could specifically target the accumulation of pathological forms of Tau in AD and related Tauopathies." (PMID 35987808, 2022). "In our in vitro tauopathy model using rTg4510 cortical neurons knockdown of Usp7 and Usp10 significantly reduced seeded TAU aggregation without affecting normal human TAU levels." (PMID 41303552, 2025).
acute myocardial infarction (1 paper, 2022). Necrosis of the myocardium, as a result of interruption of the blood supply to the area. "FOXO4 suppresses the transcription of USP10 to boost acute myocardial infarction." (PMID 35196182, 2022).
anemia (1 paper, 2016). A reduction in the number of red blood cells, the amount of hemoglobin, and/or the volume of packed red blood cells. "USP10-KO mice developed BM failure with severe anemia and died within 1 year." (PMID 27974222, 2016).
Cirrhosis (1 paper, 2025). A chronic disorder of the liver in which liver tissue becomes scarred and is partially replaced by regenerative nodules and fibrotic tissue resulting in loss of liver function. "USP10 expression was significantly down-regulated in liver tissues of patients with cirrhosis compared with healthy controls." (PMID 40873954, 2025). "Research on USP10’s role in liver fibrosis and cirrhosis is limited." (PMID 40873954, 2025).
clear cell carcinomas (1 paper, 2022).
clear cell renal cell carcinoma (1 paper, 2025). "In clear cell renal cell carcinoma, estrogen receptor β (ERβ) upregulates circAHNAK, which competitively binds USP10 to prevent FMR1 deubiquitination, leading to FMR1 degradation." (PMID 41058008, 2025).
endometrial tumors (1 paper, 2022). "USP10 showed the highest alteration frequency (6.99%) in patients with endometrial tumors with “mutation” as the primary type." (PMID 35433424, 2022).
fragile X syndrome (1 paper, 2025). A genetic syndrome caused by mutations in the FMR1 gene which is responsible for the expression of the fragile X mental retardation 1 protein. "In fragile X syndrome (FXS) and autism spectrum disorder (ASD), both USP10 and G3BP1 regulate neuronal translation through FMRP interaction, and their mutations disrupt synaptic protein synthesis, impairing cognitive function and neurodevelopment." (PMID 40785597, 2025).
intestinal cancer (1 paper, 2024). "Hence, USP10, via β-Catenin, promotes intestinal cancer stemness and propagation." (PMID 39443725, 2024).
intrahepatic cholangiocarcinoma (1 paper, 2022). A carcinoma that arises from the intrahepatic bile duct epithelium in any site of the intrahepatic biliary tree. "Usp10-Sqstm1 fusion was found in a patient with combined hepatocellular and intrahepatic cholangiocarcinoma." (PMID 35814476, 2022).
liver fibrosis (1 paper, 2025). "The therapeutic effect of MSCs-sEVs in remodeling macrophage phenotype and alleviating liver fibrosis is diminished when USP10 is knocked down, highlighting its significance." (PMID 40873954, 2025). "To further elucidate the role of USP10 in MSC-sEV-mediated alleviation of liver fibrosis, we used lentiviral short hairpin RNA (shRNA) to knock down USP10 in MSCs and harvested sEVs from the cell supernatants." (PMID 40873954, 2025). "Collectively, these data demonstrate that engineered USP10-sEVs efficiently ameliorated liver fibrosis in vivo." (PMID 40873954, 2025). "So, it would be interesting to use surface modifications to enhance the targeting of HSCs to further evaluate the therapeutic effects of USP10-sEVs for liver fibrosis." (PMID 40873954, 2025). "Subsequently, we assessed the therapeutic potential of USP10-sEVs in liver fibrosis mice." (PMID 40873954, 2025). "Mass spectrometry analysis showed that ubiquitin-specific peptidase 10 (USP10) was significantly enriched in MSCs-sEVs, which was critical for protection against liver fibrosis." (PMID 40873954, 2025).
metastatic melanoma (1 paper, 2011). A melanoma that has spread from its primary site to another anatomic site. "The expression of three out of four analyzed genes (USP10, USP11, USP22) was significantly higher in metastatic melanoma compared with benign nevi and primitive tumors, suggesting that their expression is associated with a more aggressive and invasive phenotype." (PMID 21283576, 2011).
multiple system atrophy (1 paper, 2018). Multiple system atrophy (MSA) is a neurodegenerative disorder characterized by autonomic failure (cardiovascular and/or urinary), parkinsonism, cerebellar impairment and corticospinal signs with a median survival of 6-9 years. "We also examined USP10 immunoreactivity for oligodendroglial cytoplasmic inclusions (GCIs) in multiple system atrophy (MSA), another representative disorder of synucleinopathy." (PMID 30469013, 2018).
ovarian serous adenocarcinoma (1 paper, 2024). An adenocarcinoma that arises from the ovary and is characterized by the presence of malignant epithelial cells that, in well differentiated tumors, resemble the epithelium of the fallopian tube or, in poorly differentiated tumors, show anaplastic features and marked nuclear atypia. "One case of ovarian serous adenocarcinoma had a breakpoint at the end of exon 2 with USP10 as the partner, and the other case had an intron 17 breakpoint leading to exon 18 truncation like the present case." (PMID 39759134, 2024).
ovarian tumor (1 paper, 2022). "Another exciting finding of this study was that the USP10 protein level was significantly lower in ovarian tumor tissues than in adjacent tissues." (PMID 35433424, 2022).
PN tumors (1 paper, 2023). "In comparison to primary PN tumors, MES tumors showed significantly elevated levels of USP10 and RUNX1." (PMID 36949071, 2023).
pneumonia (1 paper, 2024). An acute, acute and chronic, or chronic inflammation focally or diffusely affecting the lung parenchyma, caused by an infection in one or both of the lungs (by bacteria, viruses, fungi, or mycoplasma.). "Pseudomonas aeruginosa secretes the bacterial toxin Cif, which inhibits USP10, leading to decrease USP10-mediated deubiquitination of CFTR and increase CFTR degradation in lysosomes, causing the weaker mucociliary clearance and the harder removal of pathogens to cure pneumonia." (PMID 38322269, 2024).